IL10 (interleukin 10)
Diseases named in the same sentence as IL10 in open-access papers (continued):
Sharing a sentence is not in itself a finding about the gene and the disease.
infection (continued). "At 2 weeks post infection following needle inoculation in the ear, Axl-/-Mertk-/- mice showed significanly decreased IL-10 production from both CD4+ and CD8+ T cells which was accompanied by increased frequencies of IFNγ and iNOS expression from CD4+ T and myeloid cells, respectively." (PMID 33137149, 2020). "In general, although the levels of murine anti-inflammatory IL-4 and IL-10 cytokines were low in all groups before infection, examination of the IFN-γ/IL-10 ratios showed that the values were higher following ChimeraT/saponin immunization when compared to the individual proteins." (PMID 32821440, 2020). "Therefore, the observed reduced B cell numbers in TgAlbCre-IL10-/- mice at the later phase of infection is most likely due to a higher/persistent inflammatory immune response." (PMID 32012211, 2020). "• Splenic CD11chiMHCIIhi cDCs collected at days 21 and 28 post-infection express high IL-27 levels. • The DC-derived IL-27 may enhance the IFN-γ+ IL-10+ CD4+ cell polarization in vivo." (PMID 32849534, 2020). "NLRC5, which can act as a negative modulator of inflammatory pathways, is critical for LPS-induced IL-10 production in macrophages, which upregulated in PmCQ2 infection, which suggests it might contribute to the lower inflammatory reaction in PmCQ2 infection." (PMID 32851030, 2020). "Serum IL-10 levels were significantly higher on day 7 in patients with systemic or local infection." (PMID 32106601, 2020). "IL-10-/- C57BL/10 mice are unable to counteract the inflammatory effects of IFN-γ induced by the infection with the ME-49 strain by the intraperitoneal route, and succumb during the acute stage of the disease with enhanced liver pathology and IL-12 and IFN-γ production." (PMID 32295126, 2020). "The age of the animals at the time of blood collection had a limited effect, showing the more intense IL-1β response of monocytes from younger and older cats, and higher IL-10 mRNA levels in the monocytes of younger cats during the first six hours after infection." (PMID 33121170, 2020). "Importantly, though IL-10 is expressed following primary WT L. monocytogenes infection, WT infection still results in the generation of a robust protective immune response." (PMID 32634175, 2020). "Hence, inactivation of the pepP gene did not compromise the colonization properties of C. jejuni in the colon, duodenum, and stomach, but decreased this ability in the ileum following peroral infection of microbiota-depleted IL-10−/- mice." (PMID 32584649, 2020). "The work presented in this study reveals one mechanism employed by Malat1 to shape immunity to infection and indicates that this lncRNA, like IL-10, plays a critical role in controlling the fragile equilibrium between effective pathogen clearance and enhanced immunopathology." (PMID 32321759, 2020). "While, partly, MCMV could cause cell death during the course of its replicative cycle, the number of Bregs (IL-10 producing B-cells) was reduced further due to infection." (PMID 32455939, 2020). "A more in-depth analysis of the liver at this stage of infection revealed that TgAlbCre-IL10-/- mice had less hepatocytes, but the remaining hepatocytes showed a strongly increased pro-inflammatory gene expression and protein secretion as compared to WT or LysMCre-IL10-/- mice." (PMID 32012211, 2020). "Furthermore, the number of circulating B cells was found to be similar in both groups of mice and was only significantly reduced in TgAlbCre-IL10-/- mice at later stages of infection." (PMID 32012211, 2020). "In line with the idea of recognition of postmortem PAMPs, the secretion of IL-10 following infection of mice with Δhly could represent a strategy to prevent an unnecessary immune response to bacteria that are already dead, and thus do not pose a threat." (PMID 32634175, 2020). "Therefore, assessing the levels of IL-10 can help predict the incidence of postoperative infections." (PMID 33228727, 2020).
infection (continued). "Additionally, we observed an infection-induced increase in polyfunctional CD4+ T cells in the resistant SV/129 model, opposing an infection-induced increase in CD4+IL-10+ cells in susceptible BALB/c mice." (PMID 30881923, 2019). "The biological relevance of this transient effect of IL10 on intracellular M. bovis is unclear and could only be resolved in the context of in vivo infections involving the entire immune system." (PMID 31527895, 2019). "Hence, the protease-inactive htrA point mutant C. jejuni strain caused less pronounced colonic apoptosis and immune cell responses, but enhanced epithelial proliferation upon peroral infection of secondary abiotic IL-10−/− mice." (PMID 30984628, 2019). "We further assessed whether the disease development upon peroral infection of secondary abiotic IL-10−/− mice differed between 11168HtrA−S197A mutant and 11168WT strains." (PMID 30984628, 2019). "However, PRRSV-induced IL-10 inhibition was abolished when the cells were pre-treated with tulathromycin at 2 and 12 hours post infection." (PMID 31442273, 2019). "In the absence of IL-10 cytokine, the Il10−/− mice become highly susceptible to enteric bacterial pathogens, and show a heightened inflammatory response to pathogen infection." (PMID 31046668, 2019). "The presence of IL-10-producing neutrophils in secondary lymphoid tissues in both grass-fed and grain-fed cattle, especially in the spleen, suggests their participation in immune homeostasis as well as infection responses." (PMID 31889109, 2019). "Our findings highlight the complexity of the IL-10 immunoregulatory response and suggest that more than one cell type may be required to respond to IL-10 at different stages during infection." (PMID 30640950, 2019). "IL-10 production from effector T cells represents an essential negative feedback mechanism in the self-limitation of excessive inflammatory responses in many infections." (PMID 30984194, 2019). "Approximately 7% of T cells were IL-10-GFP positive at D6 post-infection." (PMID 31803193, 2019). "However, the infection of murine bone marrow-derived DCs with DCL-derived L. mexicana amastigotes not only promoted higher expression of IL-10 but also of IL-12 and TNF-α." (PMID 31847221, 2019). "Although there was a significant increase in the frequency of GFP+ IL-10-expressing B10 cells in the spleens of Ctrl × tiger mice after C. albicans infection, the number of splenic IL-10-expressing B10 cells remained similar in Ctrl × tiger mice after infection." (PMID 31474988, 2019). "We hypothesized that the greater expression of IL10 in response to G18 infection may be a mechanism by which G18 silences the bMDM response to infection." (PMID 31527895, 2019). "There was also a decrease in IL-4, IL-6, IL-10, and IL-13 in the late stages of infection." (PMID 31192210, 2019). "However, this persistent type 2 response shifts to long-lasting chronic infection, characterized by a strong regulatory response with expanded frequency of regulatory T cells and production of IL-10, peaking at day 28 post-infection." (PMID 30685251, 2019). "The STAT3 targets that increased in the early infection were mainly inflammatory regulators including pro-inflammatory factors IL1B, IL6 and immunosuppressive factor IL10, which might contribute to the immune regulatory role of glia in CNS during infection." (PMID 31575039, 2019). "In general, IL-10 exerts a pleiotropic effect to ensure a balance between pro- and anti-inflammatory immune responses in the context of a changing host environment during infection." (PMID 31547585, 2019). "On the other hand, olmesartan decreases IL-1β and TNF-α and increases IL-10, which could help the parasite establish an infection by decreasing the levels of proinflammatory cytokines." (PMID 31666114, 2019).
infection (continued). "While the delayed production of IL-24 by activated astrocytes is similar to the production of IL-10 and IL-19 by these cells following infection and is consistent with a role in infection resolution, we have directly assessed the effect of this cytokine on inflammatory astrocyte responses." (PMID 30825881, 2019). "Melatonin treatment (30 nM) reduced the levels of IL-6 (2-fold), MCP-1/CCL2 (5-fold), and RANTES/CCL5 (6-fold) compared to vehicle treatment after both 4 and 24 h of infection, while both vehicle and melatonin treatment reduced the levels of IL-10, MIP-2/CXCL2, and KC/CXCL1." (PMID 30949455, 2019). "Even though lethal infection induces a marked production of the proinflammatory cytokine IL-1β by monocytes, this is contrasted by the expression of considerable amounts of mRNA for the regulatory cytokine IL-10 by these cells." (PMID 31570561, 2019). "Due to its anti-inflammatory properties, IL-10 acts to downregulate excessive effector activities of both T cells and macrophages, which are key cells that are involved in the production of inflammatory cytokines following infection with African trypanosomes." (PMID 31824512, 2019). "Also, the M2 stimulus, IL-10, exacerbates EBOV infection as IL-10 knockout mice have reduced EBOV load in some organs at late times during infection and have better survival than wild-type mice." (PMID 31825972, 2019). "Notably, there have been studies showing IL-10 production by NK cells during various models of infections such as MCMV, Toxoplasma gondii, Leishmania donovani, and HIV." (PMID 31803193, 2019). "Interestingly, in contrast to what was observed for these pro-inflammatory mediators, the transcription of the anti-inflammatory cytokine IL-10 was markedly upregulated during infection." (PMID 31552007, 2019). "The lack of IL-10 has been related to lower B. abortus survival at early stages of infection and linked to the regulation of IFN-γ at later stages." (PMID 30804100, 2019). "In order to determine whether NK cell-derived IL-10 can regulate T cell activation during infection, we measured the IFNγ production by T cells." (PMID 31803193, 2019). "The reduced oocyst production after challenge infection in recombinant Eimeria immunized birds may be related to the reduced serum IL-10 level." (PMID 31300007, 2019). "In contrast, at 20 h after infection brain levels of IL-6 (19.30 vs. 6.76 ng/mg tissue, P = 0.004), IL-10 (0.88 vs. 0.27 ng/mg tissue, P = 0.013), MIP-2 (15.56 vs. 7.48 ng/mg tissue, P = 0.023) and KC (31.55 vs. 10.43 ng/mg tissue, P = 0.019) were increased in Cfh−/− mice compared to wt mice." (PMID 31883521, 2019). "Future studies including rescue experiments transferring defined populations of IL-10R competent cells in IL-10 signalling-deficient mice or using inducible conditional knockout mice at different times during infection will help to identify the critical IL-10 responsive cell(s)." (PMID 30640950, 2019). "However, macrophage response is often hampered by the production of IL-10, a potent suppressor of the host immune response, which was reported to be correlated with TB pathogenesis and persistent of infection in humans." (PMID 31921181, 2019). "In PRRSV, the role of Tregs remains unclear and appears to be a consequence of IL-10 induction of some strains as early as 2 days post infection." (PMID 30842948, 2019). "Taken together, our demonstration that IL-10 overexpressing UC-MSCs can enhance therapeutic effects in a clinically relevant infection model suggests that this approach deserves further exploration as a potential therapy for infection-induced ARDS." (PMID 31200579, 2019). "Interestingly, the percentage of IL-10 expressing AMs further decreased significantly as infection progressed into the chronic stage." (PMID 31333668, 2019). "Moreover, during the recovery phase of infection, BG stimulates the production of IL-10 to decrease excessive immune activation and minimize potential host tissue damage." (PMID 31412594, 2019).
infection (continued). "Furthermore, Suzuki and colleagues reported inflammatory changes within the large intestines following peroral infection of IL-10−/− mice with 20 cysts of the ME49 strain." (PMID 31032232, 2019). "This study was aimed at defining whether UPEC flagella, typically associated with motility and bacterial adherence, are sensed by the bladder innate immune system as part of a defense strategy utilizing IL-10 to control infection." (PMID 31776239, 2019). "In the case of S. Typhimurium infection, for example, IL-10 may suppress the bactericidal response of macrophages against the infection." (PMID 31277323, 2019). "We detected levels of IL-10 in the supernatant by ELISA at 48 h after infection of hAMSCs." (PMID 31281390, 2019). "However, IL10 was found to promote survival of both M. bovis strains during early bMDM infection, but this effect disappeared after 24 h." (PMID 31527895, 2019). "Infiltrating monocytes could be infected by B. abortus and then secrete proinflammatory cytokines and a low amount of IL-10 in response to this infection." (PMID 31695682, 2019). "Moreover, lung levels of IL-10 and IL-12p40 remained reduced on the sixth day of infection when compared to the PBS control in A/J C5−/− mice." (PMID 31687410, 2019). "The distribution of the polymorphisms of CRP, TNF, and IL10 genes showed no significant changes irrespective of a previous infection or not with Chlamydia." (PMID 30804931, 2019). "However, NK cells in PKO X IL-10-GFP mice produced high amounts of IL-10 from day 4 to day 8 post-infection before starting to decrease." (PMID 31803193, 2019). "The high levels of TNF and the decreased ability of IL-10 to down regulate cytokine production leads to an exacerbation of the inflammatory reaction and development of cutaneous and mucosal leishmaniasis following infection with L. braziliensis." (PMID 31119102, 2019). "The induction of iNOS in macrophages in vitro, and the expression of Arginase-1 and of IL-10 in vivo, was not altered in MyD88-deficient cells/mice after infection with NMII." (PMID 30800124, 2019). "The demonstration that IL-10 overexpression can enhance UC-MSCs’ therapeutic effects in a clinically relevant infection model and enhance human macrophage function via this mechanism suggests that this approach deserves further exploration as a potential therapy for infection-induced ARDS." (PMID 31200579, 2019). "However, in the later phase of the infection, regulatory mechanisms (evidenced by IL-10) are activated and downregulate expression of inflammasome components, as observed in this study." (PMID 30901375, 2019). "It is important to know if changes in IL-10, induced by a concomitant infection, may influence the clinical outcome of EVD." (PMID 31547585, 2019). "Production of IFN-γ and IL10 have key roles in the course of infection by Babesia sp." (PMID 30800644, 2019). "The transient effect of IL10 on M. bovis intracellular growth described here differs from a previous study which found that the addition of anti-IL10 antibody resulted in a significant reduction in M. bovis replication five days post infection." (PMID 31527895, 2019). "Both, IL-12 and IFN-γ production are essential for the host to survive infection with T. gondii, and the control of these proinflammatory mediators is achieved by the induction of anti-inflammatory cytokines such as IL-10." (PMID 31867288, 2019). "Indeed, in hamster models of Leptospira infection, it has been shown that there is an initial Th1 response followed by a predominance of high IL-10 at later stages of the infection." (PMID 31114579, 2019). "Interestingly, blocking IL10 during G18 infection resulted in elevated expression of these two cytokines to similar levels measured during AF2122/97 infection." (PMID 31527895, 2019).
infection (continued). "In our experiments, IL-10-producing B cells induced after C. muridarum stimulation exhibited innate-like B cell characteristics since they were rapidly induced during the course of the infection and depended on TLR4 signaling." (PMID 30881362, 2019). "However, the frequency of splenic GFP+ IL-10-expressing B10 cells in Cko × tiger mice was unchanged after infection, whereas the number of these cells was significantly higher than in Ctrl × tiger mice." (PMID 31474988, 2019). "IL-10 was shown to play contrasting roles during S. aureus systemic and localized infections with prevention of bacterial dissemination and tissue damage due to T cell effector function or promotion of bacterial persistence by controlling T cell effector function, respectively." (PMID 31134074, 2019). "In addition, the levels of pro-inflammatory cytokines (IL-2, IL-6, IL-12, TNF-α, IFN-α, IFN-γ) were higher in il10−/− mice than in wild-type mice at 1, 3, and 6 h post infection." (PMID 31551984, 2019). "Defining the mechanism of engagement of the immune system by the bacteria that enables the protective IL-10 response is critical to exploring how we might exploit this mechanism for new infection control strategies." (PMID 31776239, 2019). "Interestingly, the production of IL-1β in T. gondii-infected cells treated with SF was significantly increased and the expression of IL-10 was gradually decreased compared with the infection group." (PMID 31075881, 2019). "Lower HLA-DR expression and elevated IL-10 level were found in secondary infection group." (PMID 31627725, 2019). "Another key cytokine that regulates the outcome of infection with African trypanosomes is IL-10." (PMID 31824512, 2019). "We reported that robust IL-10 expression was detected in the first week of STFTV infection in the deceased patients, in contrast to a significantly lower level in the convalescent patients, suggesting a causative relation between elevated IL-10 and miR-146a/b and the pathogenesis of SFTSV infection." (PMID 31156641, 2019). "In this study, we confirmed that PCV2 could also induce IL-10 production in mice to promote infection, as well as in piglets." (PMID 31551984, 2019). "In addition, treatment with the ERK1/2 inhibitor decreased NO and TNF-α production, whereas it slightly increased IL-10 production in pasakbumin A-treated Raw264.7 cells during H37Rv infection, similar to the effect observed in cells infected with H37Rv alone." (PMID 30865638, 2019). "Infection by the mucosal route often results in minimal tissue damage, in part because infection by this route preferentially induces regulatory T cells and cytokine responses such as IL-10 producing macrophages." (PMID 31636623, 2019). "High levels of IL-10 were detected in culture supernatants of mononuclear cells (either from spleen or prostate draining lymph nodes) from infected NOD at early days after infection, reaching peak levels at 4–7 dpi." (PMID 30881362, 2019). "In contrast, melatonin reduced IL-10 levels, which could correlate with immune response modulation induced by infection and pathogenesis." (PMID 30949455, 2019). "Early in an infection (before day 15 p.i.), IL-10 signalling-deficient mice, infected with T. muris, lacked the type-2 response and goblet cell hyperplasia observed in WT mice." (PMID 30640950, 2019). "In IL-10-GFP mice, IL-10 production by T cells was acute and peaked at day 6 post-infection." (PMID 31803193, 2019). "Moreover, those mice that showed the highest capability to secrete IL-10 (NOD mice) were the least efficient in clearing the infection." (PMID 30881362, 2019). "However, in C57BL/6-macrophages, the levels of Il1b, Tnf, Il10, and Il6 receptor transcripts increase during infection." (PMID 30949455, 2019). "However, our data showed that LpxO-mediated hydroxylation contributes to the expression of IL-10 in macrophages following infection." (PMID 30745327, 2019).